KRTAP4-16 (keratin associated protein 4-16)
Description:
In the hair cortex, hair keratin intermediate filaments are embedded in an interfilamentous matrix, consisting of hair keratin-associated proteins (KRTAP), which are essential for the formation of a rigid and resistant hair shaft through their extensive disulfide bond cross-linking with abundant cysteine residues of hair keratins. The matrix proteins include the high-sulfur and high-glycine-tyrosine keratins.
Synonyms: KRTAP4-16P; KRTAP4P1; KAP4A
Tractability: No criterion of Open Targets' tractability assessment is met for any kind of drug.
Gene: Protein-coding gene on chromosome 17 (41,101,502 to 41,102,209, reverse strand). Ensembl gene ENSG00000241241.
Gene Ontology:
Biological process: hair cycle
Cellular component: cytosol; keratin filament
Genetic constraint (gnomAD): Missense variants: 211 observed, 165.25 expected, observed/expected ratio (o/e) 1.28, 90% interval 1.14 to 1.43. Synonymous variants: 78 observed, 62.53 expected, observed/expected ratio (o/e) 1.25, 90% interval 1.04 to 1.51.
Homologues: Orthologues: mouse Krtap5-24 (23% identical), mouse Krtap5-26 (20% identical), mouse Krtap5-2 (20% identical), mouse Krtap5-20 (18% identical), rat Krtap5-8 (18% identical), rat AABR07006049.1 (17% identical). Paralogues in human: KRTAP4-11 (50% identical), KRTAP4-8 (49% identical), KRTAP4-9 (49% identical), KRTAP4-3 (35% identical), KRTAP4-4 (34% identical), KRTAP4-5 (33% identical), KRTAP4-12 (32% identical), KRTAP4-6 (32% identical), KRTAP4-7 (31% identical), KRTAP4-2 (29% identical), KRTAP4-1 (26% identical), KRTAP10-9 (23% identical), and 35 more.